ENSG00000285827 (novel protein)
Gene: Protein-coding gene on chromosome 11 (118,401,602 to 118,482,737, forward strand). Ensembl gene ENSG00000285827.
Genetic constraint (gnomAD): Loss-of-function variants: 2 observed, 69.54 expected, observed/expected ratio (o/e) 0.0288, 90% interval 0.011 to 0.091. Missense variants: 749 observed, 1,147.3 expected, observed/expected ratio (o/e) 0.65, 90% interval 0.61 to 0.69. Synonymous variants: 362 observed, 432.25 expected, observed/expected ratio (o/e) 0.84, 90% interval 0.77 to 0.91.